BACH1 (BACH transcriptional regulator 1)
Diseases named in the same sentence as BACH1 in open-access papers (continued):
Sharing a sentence is not in itself a finding about the gene and the disease.
tumor (continued). "Bach1 enzyme activity as well as the BRCA1-FancJ interaction is essential for DNA repair, checkpoint activation and tumor suppression." (PMID 22369660, 2012). "Weak expression of JMJD1A and BACH1 were observed in nuclear of NPC tumor cells, while strong expression of JMJD1A and BACH1 were observed in normal adjacent nasopharyngeal epithelium." (PMID 21541331, 2011). "These target genes are known to participate in tumor progression, but the suggested regulatory roles of PAX4, BACH1, BACH2, MAZ and TAF8 in the process is new." (PMID 21682879, 2011). "Moreover, depleting SDCBP leads to upregulation of BACH1-repressed electron transport chain (ETC) genes, such as NDUFA4 and COX6B2, and increases mitochondrial activity, enhancing anti-tumor efficacy of metformin against TNBC both in vitro and in vivo." (PMID 40263598, 2025). "Immunohistochemical staining revealed that treatment of the 4T1 tumor with adenoviral SDCBP shRNA significantly decreased the expression levels of SDCBP, BACH1, and Ki67, but increased the expression levels of NDUFA4 and COX6B2 compared with those in the control and metformin-treated groups." (PMID 40263598, 2025). "The transcription factor Bach1 (BTB Domain And CNC Homolog 1), also known as basic leucine zipper transcription factor 1, is highly expressed in tumors such as breast and lung cancers compared to their non-tumor tissues." (PMID 39905004, 2025). "The mean value of BACH1 IHC scores was markedly higher in the basal-like subtype than other subtypes of tumors among Black women, whereas the mean BACH1 scores were quite similar regardless of tumor subtype among White women." (PMID 40710214, 2025). "In in vivo studies, BACH1-depleted MB436 tumor xenografts were treated with or without metformin in athymic nude mice." (PMID 40430851, 2025). "No change in tumor size in either BACH1-depleted or metformin alone was observed as compared to the control." (PMID 40430851, 2025). "BACH1 expression shows a positive correlation with tumor size, whereas MCT1 expression was not significantly correlated with tumor size." (PMID 40710214, 2025). "FLK4, BACH1, and GMEB2 were important regulators of C0 RPS4Y1+ tumor cells." (PMID 40230840, 2025). "Notably, the Keto diet–induced tumor metastasis is dependent on BTB domain and CNC homolog 1 (BACH1) and its up-regulation of pro-metastatic targets, including cell migration–inducing hyaluronidase 1, in response to the Keto diet." (PMID 38838145, 2024). "If cell lines represent inter-patient or intra-tumor diversity, then intermediate BACH1 expression in MB231 cells suggests that BACH1 suppression might boost invasiveness in TNBC." (PMID 37231268, 2023). "Notably, BACH1 also functions as a tumor suppressor and controls growth and survival of AML cells by regulating HO-1 expression, suggesting that functional upregulation of BACH1 is a potential strategy for antileukemic therapy." (PMID 36774506, 2023). "In addition to inhibiting HCV replication and IR injury and promoting mucosal protection and antiviral response, BACH1-mediated HO-1 upregulates the expression of VEGF and other molecules and downregulates PTNE expression to regulate tumor angiogenesis." (PMID 37228820, 2023). "The positive rates of BACH1 in the adjacent nontumor and tumor tissues were 9.7% (28/289) and 31.5% (181/574), showing significant overexpression of BACH1 in ESCC." (PMID 36670112, 2023). "Aside from oxidative stress, BACH1 has been shown to participate in the cell cycle, angiogenesis, metabolism regulation, and EMT, thus contributing to tumorigenesis and metastasis, although the results are controversial in different tumor types." (PMID 36670112, 2023). "The effect of DC101 on BACH1–/– tumors was not significant, although the drug tended to reduce a delayed tumor growth increase." (PMID 37651203, 2023).
tumor (continued). "Thus, we noticed that overexpression of MALAT1 and BACH1 was detected in TNBC with poor prognostic variables such as tumor size, nodal metastasis, and advanced tumor stage." (PMID 35096427, 2022). "The results showed that BACH1 knockdown significantly inhibited the density of CD31+ blood vessels and VEGFC expression in xenograft tumor tissues derived from mice subcutaneously injected with KYSE170‐shBACH1 cells compared with those derived from mice injected with control KYSE170‐shCtrl cells." (PMID 33932125, 2021). "The expression of BACH1 was weak or moderate in the noncancerous tissues and moderate or strong expressed in the tumor tissues." (PMID 33932125, 2021). "In contrast, mouse models bearing mutant Bach1-expressing TNBC tumors did not suppress tumor size when both metformin and hemin were administered, because hemin did not interact with mutant Bach1." (PMID 33809182, 2021). "Finally, we addressed the molecular basis of the BACH1 and VEGFC interaction during tumor progression in the various mouse tumor models." (PMID 32132179, 2020). "The mRNA levels of all molecules and the detectability of Bach1 mRNA in both the tumor and normal tissues were not different between subjects with and subjects without distant metastasis." (PMID 27999449, 2016). "In the absence of detectable Bach1 mRNA expression, the mRNA levels of Keap1, but not Nrf2, retained significant correlation with that of Hmox1 in the tumor tissue of CRC." (PMID 27999449, 2016). "Since BACH1 levels were higher in the basal-like tumor subtype, we investigated whether BACH1 expression levels differed by tumor invasiveness or between metastatic and non-metastatic tumors." (PMID 40710214, 2025). "Taken together, BACH1 is expressed significantly more in tumors from Black patients than in those from White patients, and it is particularly highest in the basal-like tumors from Black women, regardless of tissue type or tumor grade." (PMID 40710214, 2025). "We estimated a PO-OLR to evaluate whether race affected BACH1 expression, while controlling for tissue type (metastatic vs. non-metastatic) and histological grades (tumor grade)." (PMID 40710214, 2025). "Therefore, Keto diet–mediated regulation of ferroptosis and tumor growth does not support the notion that BACH1-mediated ferroptosis is required for its effect in modulating tumor metastasis although further investigations are clearly needed." (PMID 38838145, 2024). "To determine whether antioxidant-mediated BACH1 activation is functionally involved in tumor angiogenesis, we administered NAC and VitC to NSG mice harboring BACH1+/+ and BACH1–/– tumors and quantified tumor vascularity by ultrasound analysis." (PMID 37651203, 2023). "Interestingly, previous studies revealed that BACH1 promotes tumor invasion and metastasis while not affecting primary tumor growth." (PMID 34262028, 2021). "Furthermore, JMJD1A and BACH1 are downregulated in NPC cell lines and NPC tumor tissues." (PMID 21541331, 2011). "The FBXO22-induced downregulation of BACH1 promotes AML progression, which means that BACH1 has a negative effect on tumor growth in this context." (PMID 38321558, 2024). "Hence, a simple suppression for BACH1 may have negative effects on tumor metastasis in some cases." (PMID 38321558, 2024). "In contrast to BACH1, NRF2 knockdown in MDA-MB-231 did not affect IL11 expression or tumor cell invasion, since it is already low in expression." (PMID 34262028, 2021). "Mice injected with P-GBM2 cells expressing vector control had a significant decrease in tumor volume when treated with TMZ, whereas tumor growth of TMZ treated xenografts overexpressing BACH1 was almost not affected." (PMID 28000777, 2016). "Additionally, although SCD1 acts as a main negative effector of BACH1-induced ferroptosis, it is a poor target because high SCD1 expression also promotes tumor cell proliferation." (PMID 36670112, 2023).
tumor (continued). "Without Bach1 expression, Keap1 may become the major regulator of Hmox1 mRNA transcription in CRC tumor tissue." (PMID 27999449, 2016). "In our LUAD models, BACH1 expression remained unchanged at both the mRNA and protein levels upon RKIP overexpression, suggesting that this interaction may not be as relevant in EGFR‐mutant LUAD, reinforcing RKIP's tumor‐specific roles." (PMID 40720248, 2025).
infection (10 papers, 2010 to 2024). The state of being infected such as from the introduction of a foreign agent such as serum, vaccine, antigenic substance or organism. "Accompanying its role in cellular necrosis, Bach1 deficiency had a major effect on murine host resistance to Mtb in both BL/6 WT high-dose and B6.Sst1S low-dose infection models." (PMID 38066332, 2024). "AAV-shBach1 infection caused efficient knockdown of endogenous BACH1 in the liver." (PMID 38129407, 2023). "To assess the functional role of Bach1 in Mtb-induced disease, we examined the outcome of Mtb infection in Bach1−/− and WT mice at different doses of infection." (PMID 38066332, 2024). "In support of these histopathological findings, analysis of RNA-seq data obtained from publicly available data revealed increased Bach1 mRNA levels in the lungs of Sst1S+C3HeB/FeJ mice following aerosol H37Rv infection." (PMID 38066332, 2024). "When aerosol infected with H37Rv strain at low dose (~150–250 c.f.u.s), Bach1−/− mice showed a small but significant increase in resistance to Mtb, with a median survival time of 250 days post infection (dpi) vs 191 d for WT control animals." (PMID 38066332, 2024). "To extend these clinical observations, we assessed Bach1 protein expression in lung tissue sections from rhesus macaques at 15–16 weeks post infection with Mtb35." (PMID 38066332, 2024). "To assess the antioxidative response of Bach1 and Nrf-2 during L. europaeus GI.1 and GI.2 genotype infection in rabbits, we estimated their effect on the downstream target gene HO-I." (PMID 38516020, 2024). "One resounding theme across in vitro infection, untreated and treated in vivo infection was heightened accessibility for AP-1 family (Fos, Jun) and Bach1/Bach2 transcription factor motifs." (PMID 36536105, 2023). "Similar results were observed in HepG2 cells when BACH1 was knocked down by infection with adenovirus interference vector of BACH1 (shBach1)." (PMID 38129407, 2023). "BACH1 expression was regulated by using lentiviral vector infection, and the efficiency was tested using qRT-PCR and Western blot analysis." (PMID 36424585, 2022). "To examine the involvement of c-Maf, Bach-1, and Elmo-1 in Mtb-growth promotion within M(IL-4/IL-13) BMDMs, we knocked-down these target genes using GapmeRs in M(IL-4/IL-13) BMDMs prior to infection with Mtb." (PMID 30941122, 2019). "Further validating our findings, we found that BACH-1 targeting by siRNA increased macrophage permissiveness for infection by approximately 70%, although overexpression of multiple miRNAs increased permissiveness by approximately 250%." (PMID 20126446, 2010). "However, a change in Bach1 expression in the spleen was noted only in infection with GI.2 and was reduced by 2.3-fold (56% reduction, p = 0.02 vs. control)." (PMID 38516020, 2024). "As iron metabolism is dynamically altered during infection, TBK1 and BACH1 may contribute to immune responses as well as EMT by altering iron metabolism." (PMID 36009179, 2022).
cardiovascular disease (8 papers, 2014 to 2025). "Although BACH1 has been implicated in angiogenesis associated with cardiovascular diseases, its specific role and underlying mechanisms in ICP remain unclear." (PMID 40312332, 2025). "The protective effect of HO-1 appears to be constrained by Bach1 under several specific disease conditions, because Bach1-deficient mice are more resistant to tissue damage than wild-type mice in the models of lung, liver, intestine, and cardiovascular diseases." (PMID 25050144, 2014). "Recent emerging evidence, however, indicate the widespread functions of BACH1 in diverse physiological and pathological settings, including hematopoiesis, inflammation, cardiovascular disease, aging, metabolic disorders, and neurodegenerative diseases." (PMID 32132179, 2020). "intervening in BACH1 may offer new therapeutic targets for cardiovascular diseases and metabolic diseases." (PMID 39887888, 2025). "Previous studies suggest that Bach1 deficiency may protect against oxidative tissue damage in murine models of lung, liver, intestine, pancreas, and cardiovascular disease, and we have shown that Bach1 suppresses angiogenesis in mice with surgically induced hindlimb ischemia (HLI)." (PMID 27057283, 2016).
neurodegenerative disease (6 papers, 2020 to 2025). A disorder of the central nervous system characterized by gradual and progressive loss of neural tissue and neurologic function. "The activation of Nrf2 and the inhibition of Bach1 can counteract ferroptosis and present a promising avenue for future therapeutic interventions targeting ferroptosis in neurodegenerative diseases." (PMID 39040474, 2024). "However, the interdependence of Nrf2/Bach1 effects on these targets in the context of neurodegenerative diseases needs to be further explored." (PMID 39040474, 2024). "In this review, we intend to pinpoint the gaps in our knowledge of the detailed mechanism of ferroptosis initiation and propagation and discuss the potential benefits of activating Nrf2 and inhibiting the Bach1 signaling pathway for counteracting ferroptosis in neurodegenerative diseases." (PMID 39040474, 2024). "There are no published studies regarding Bach1 and Bach2’s involvement in mediating ferroptosis in neurodegenerative diseases." (PMID 39040474, 2024).
metabolic disease (4 papers, 2020 to 2025). A congenital disorder (due to inherited enzyme abnormality) or acquired (due to failure of a metabolically important organ) disorder resulting from an abnormal metabolic process. "Therefore, although BACH1 seems to be associated with metabolic disorders, its specific role in hepatic insulin signaling and glucose homeostasis is unknown." (PMID 38129407, 2023).
hematological disorders (2 papers, 2021 to 2025). "BACH1 has a close connection with the genesis and hematological disorders." (PMID 39887888, 2025).
brain disorder (1 paper, 2020). A disease affecting the brain or part of the brain. "Since gender differences may influence the risk for brain disorders and the severity of their phenotypic manifestations, the role for BACH1 appears of great interest." (PMID 32839417, 2020).
immune dysfunction (1 paper, 2023). "This work has greater implications on how pathogen-driven hemolytic events influence the adaptive immune responses of their hosts via heme modulation of B cells through degradation of BACH2, and even T cells via degradation of BACH1 and BACH2, creating immune dysfunction." (PMID 37639483, 2023).
liver (1 paper, 2022). "In contrast, the effects of Bach1 in myocardial, cerebral, and liver IR injuries have already been investigated." (PMID 35326209, 2022).
BACH1 also shares sentences with these, for which no sentence is quoted: Alzheimer disease (4 papers); non-small cell lung carcinoma (3); sickle cell disease (3); Breast invasive carcinoma (2); Cerebral ischemia (2); cholangiocarcinoma (2); diabetic nephropathy (2); Hepatitis (2); inflammation (2); lupus nephritis (2); pancreatic adenocarcinoma (2); rectal adenocarcinoma (2); steatosis (2); type II diabetes (2); Warsaw breakage syndrome (2); acute leukemia (1); acute lymphoblastic leukemia (1); acute porphyria (1); Adrenocortical carcinoma (1); amyotrophic lateral sclerosis (1); anemia (1); arteriosclerosis (1); autism spectrum disorder (1); bronchopulmonary dysplasia (1); childhood cancer syndrome (1); chronic kidney disease (1); chronic myeloid leukemia (1); diffuse large B-cell lymphoma (1); eczema (1); endothelial dysfunction (1).
A further 34 diseases each share a sentence with BACH1 in 1 paper.